CCND1 (cyclin D1)
Diseases named in the same sentence as CCND1 in open-access papers (continued):
Sharing a sentence is not in itself a finding about the gene and the disease.
tumor (continued). "In these LUAD patients, the methylation of HOXA9 was significantly upregulated, whereas the methylation of KRTAP8-1, CCND1, and TULP2 were downregulated obviously in tumor samples compared with adjacent tissues." (PMID 31850197, 2019). "In three cases where tumour tissue sequencing failed, amplifications in ERBB2, FGFR2, EGFR, and CCND1 were identified in ctDNA." (PMID 31137920, 2019). "This decreases production of cyclin D1/D3 and matrix metalloproteinases (MMPs), which provides new insights into the role of LPP1 in controlling tumor growth and metastasis." (PMID 31534541, 2019). "We found that the expression of cyclin D1 and CDK4 was significantly elevated in GC tissues versus adjacent non‐tumour tissues." (PMID 30714150, 2019). "In line with the data from our cell models, a residual tumor of an anaplastic PXA case operated during combination treatment of dabrafenib and the MEK-inhibitor trametinib had lost expression of ETS1, cyclin D1 and TERT." (PMID 31391125, 2019). "The IHC results showed that STX-0119 at the dose of 80 mg/kg and 160 mg/kg reduced the expression of c-Myc and cyclin D1 protein, while only 160 mg/kg STX-0119 increased the number of apoptotic cells in tumor tissues." (PMID 32257917, 2019). "Paralleling the results of experiments with fibronectin, the expression and activity of vimentin, cyclin D1, TGF-β1, Smad, and Src are elevated in tumor tissues of RCC and show prognostic potential." (PMID 31181623, 2019). "Tumor tissue lysates of the CT26Flag−CAGE1 cells showed higher expression of Wnt1, β-catenin, pGSK3βSer9, and cyclin D1 than the tumor tissue lysates of the CT26 cells." (PMID 31799196, 2019). "Subsequently, we measure CCND1 and PECAM1/CD31 expression level in three pairs of ccRCC tumor and normal samples." (PMID 31850854, 2019). "In conformity with previous findings, our studies also indicate that inhibition of cyclin D1, CCRK and CDK2 are involved in inhibition of growth and proliferation in EMCA cells and tumor regression in mice." (PMID 30846786, 2019). "The focus of current study was to determine ER subtype specific expression on cSCC A431 cells and investigate if ER agonist based activation modulates tumor markers CD55 and Cyclin D1 in the cells." (PMID 31611744, 2019). "Further investigation revealed that the downregulation of VGLL4 upregulated the expression of apoptosis-related Bcl-2 and the cell-cycle regulators Cyclin D1, Cyclin E1, and CDK8, and the upregulation of these molecules was conducive to tumor proliferation." (PMID 31748508, 2019). "Subsequent overexpression of the Wnt downstream target genes that function in cell growth (cyclin D1 and c-Myc) and epithelial–mesenchymal transition (EMT) (E-cadherin and matrix metalloproteases) further promote the malignancy of tumor growth and metastasis." (PMID 30909473, 2019). "IHC staining revealed that up‐regulation of RN181 significantly increased the expression of p21 but dramatically reduced the expression of cyclin D1 and CDK4 in xenograft tumours of AGS cells (AGS‐RN181 versus AGS‐RV, all p < 0.01)." (PMID 30714150, 2019). "For instance, AKT activation in a breast cancer mouse model promotes tumor initiation and progression by decreasing apoptosis through phosphorylation of FOXO and increased levels of Cyclin D1." (PMID 31752925, 2019). "In this study, we systematically analyzed the DNA methylation data of LUAD and found that the hypermethylation of HOXA9 and the hypomethylation of KRTAP8-1, CCND1, and TULP2 were observed in LUAD tumor samples." (PMID 31850197, 2019). "Immunohistochemical analysis revealed that overexpressing miR-330-3p increased PCNA, cyclin D1, CD44 and β-catenin, and reduced cleaved caspase-3 and Bax in tumor tissues." (PMID 31498117, 2019). "Further more, we confirmed decreased expression of CTNNB1 downstream transcription factor TCF4 and target gene Cyclin D1 in METTL3 knockout HB cell Huh6 and tumor-bearing tissues of mice." (PMID 31870368, 2019).
tumor (continued). "The results further confirmed that the hypermethylation of HOXA9 and the hypomethylation of KRTAP8-1, CCND1, and TULP2 were observed in LUAD tumor samples." (PMID 31850197, 2019). "In addition to these well-known tumor suppressors, some circRNAs could also regulate tumor growth by regulating cell cycle mediators, such as Cyclin D1, a well-known regulator of the cell cycle that promotes the transition from G1 to S phase by activating CDK4 or CDK6." (PMID 30999909, 2019). "The tumor tissues isolated from those nude mice were further immunized with four antibodies: DACH1, CXCL1, cyclin D1, Ki67." (PMID 31998654, 2019). "Nintedanib effect leading to cell cycle arrest was confirmed in vivo, as shown by decreased Cyclin D1 levels and proliferation rate of tumor cells in PC3 xenografts, which contributes to reduced tumor volume in animals that received the drug." (PMID 29934570, 2018). "Further, we show that agrin silencing interferes with cancer cell motility, proliferation, invasion, colony and tumour spheroid formation, and it also reduces the phosphorylation of FAK, ERK and cyclin D1 proteins in OSCC cells." (PMID 29872149, 2018). "Our results show that increased TRIM24 in HNSCC plays an important role in tumor metabolism and progression, possibly through regulation of GLUT3 and cyclin D1." (PMID 29862279, 2018). "The expression of proto-oncogenes in immortalized-human epithelial cells, such as CCND1 or FRA-1, is sufficient to stimulate the anchorage-independent growth, yet are insufficient to result in tumour formation in mice." (PMID 30451834, 2018). "p-4EBP1, the inactivated form of 4EBP1, might act as a tumor promoter by converging upstream oncogenic signals and driving the proliferative signal downstream, initiating the synthesis of oncogenic proteins such as cyclin D1, c-myc, or vascular endothelial growth factor (VEGF)." (PMID 29416809, 2018). "Further DY131 treatment of xenograft tumor samples led to decreased expression of Ki67, the three Wnt components (TCF4, LEF1, and β-catenin), and the CCND1 Wnt downstream target gene." (PMID 29765046, 2018). "For the decreased cyclin D1 and CDK 4/6 levels found in tumor tissue, these proteins can serve as biomarker for erufosine intervention." (PMID 29464035, 2018). "We next assessed classical tumour proliferation proteins, including PCNA, c‐myc, cyclin‐A1 and cyclin‐D1, by western blot." (PMID 29435409, 2018). "Immunohistochemical staining of xenograft tumor tissues was conducted to evaluate the protein abundance of DACH1, cyclin D1, Ki-67, and CXCL8 in DACH1-overexpressed and control tumors." (PMID 29636079, 2018). "Proteins in this cell proliferative pathway include p16, an endogenous suppressor of CDK4/6, cyclin D1, the regulatory subunit of CDK4/6, and retinoblastoma (Rb) protein, a tumor suppressor." (PMID 30322180, 2018). "The cliques involving AKT1 (METH), PTEN (mRNA) and AKT1 (METH), PIK3R2 (mRNA) can be construed as tumor suppressing, while cliques involving AKT1 (METH), CCND1 (mRNA) and AKT1 (METH), GRB2 (CN) probably are tumor activating." (PMID 30059495, 2018). "Among three analyzed tumor-related genes, CTNNB1 and MET act as the oncogenes in HCC, and CCND1 is the hallmarker of cell cycle procession." (PMID 30327605, 2018). "Let-7 exerts its tumor suppressor activity by regulating different oncogenes including MYC, RAS and CCND1." (PMID 30286096, 2018). "Molecular analysis of the tumor tissues showed that melatonin decreased the levels of p-Akt, p-ERK, cyclin D1, PCNA, Bcl-2, Vimentin, Snail, HIF-1α, and VEGF, but upregulated the expressions of Bax and E-cadherin." (PMID 29725496, 2018). "We measured ascorbate, HIF-1α, and HIF-2α protein and HIF downstream targets BNIP3, CA9, cyclin D1, GLUT1, and VEGF (combined to generate the HIF pathway score) in VHL-defective ccRCC (n = 73) and VHL-proficient pRCC human tumor tissue (n = 41)." (PMID 30555801, 2018).
tumor (continued). "Western blotting revealed that the expression of β‐catenin, TCF1, cyclin D1, AXIN2 and MMP7 was remarkably reduced in shTRIM32‐inoculated tumour tissues." (PMID 30079558, 2018). "URG11 has been reported to be the upstream activator to promote tumor growth; inhibition of URG11 decreased the expression level of β-catenin and the downstream targets including c-Myc, cyclin D1, and MMPs." (PMID 29955600, 2018). "For both CCND1 and PDGFRA, staining within Group 2 tumours was most prominent within the “oligodendrocyte-like” cell population often described within DNETs." (PMID 29058119, 2018). "NF-κB target gene encoding proteins such as MMP-9, VEGF, MCL-1, XIAP, C-FLIP, and Cyclin-D1, promote metastasis, angiogenesis, antiapoptosis, and proliferation in HCC leading to tumor progression." (PMID 29535278, 2018). "To further confirm the tumour inhibition mechanism of PF, we examined the expression of Ki67, PCNA, β-catenin, Cyclin D1 and c-Myc in the tumour tissue." (PMID 29789528, 2018). "A decrease by 90% in the cyclin D1, CDK4 and CDK6 levels was observed in the erufosine treated tumor samples." (PMID 29464035, 2018). "The most recurrent focal amplified region was 11q13.3 including the CCND1 and FGF3 genes amplified in 40% of samples (60/66 with smoking history), consistent with a region preferentially amplified on smoking related tumours." (PMID 29377909, 2018). "Our results found that BSYX induced an increase in the expression levels of FSHR, Akt/p-Akt, Gankyrin, and cyclin D1 proteins and a decrease in HIF-α in mice tumor." (PMID 30402135, 2018). "We validated the focal status of gene amplification (size < 10Mb) for 2 tumours (focal amplification of CCND1 for tumour T8 and focal amplifications of DDR2, AKT2 and MDM2 for tumour T16) using array comparative genomic hybridization." (PMID 29416628, 2018). "BPIFB1 is a potential tumor suppressor that regulates NPC cell growth by downregulating the MAPK and cyclin D1/E2F pathways." (PMID 29568064, 2018). "By integrating genomic and transcriptomic studies of NPC PDX model, we were able to discover copy number of CCND1 and CDKN2A are the potential drug target of CDK inhibitor, palbociclib, to suppress tumor growth." (PMID 30236142, 2018). "Knockdown of NEAT1 up-regulated the tumor suppressor miR-34c to inhibit cell proliferation, induce apoptosis, and cell cycle arrest via BCL-2 and cyclin D1 pathway, which elevated the sensitivity to DDP-induced chemotherapy for tumor regression." (PMID 29654165, 2018). "Tumor necrosis appeared correlated to INA expression and Cyclin D1 overexpression (p = 0.01 and p = 0.04 respectively)." (PMID 29489901, 2018). "On the contrary, cyclin D1 overexpression was also reported to be correlated with apoptosis under specific concomitant signals of arrest such as serum starvation or proliferation arrest, which may due to the feedback loop between cyclin D1 and tumor suppressors." (PMID 30279365, 2018). "Expression of CDK4 and cyclin D1 was increased in tumor sections with SKA3 overexpression (vs. control vector, **p < 0.01) but decreased in tumor sections with SKA3 knockdown." (PMID 30459531, 2018). "The calculated genomic circuit scores were, as expected, high for tumours in the Uro cluster, i.e. FGFR3+, CCND1+, RB1+, and E2F3−, both at the mRNA level and the tumour‐cell protein level." (PMID 28195647, 2017). "Celecoxib treatment also decreased the expression levels of Wnt pathway components and target genes, such as β-catenin, p-GSK-3β, MMP-2, Survivin, AXIN2, CYCLIN-D1 and C-MYC, and the CSC marker SOX-2 in the xenograft tumor tissues." (PMID 29383157, 2017). "Cancer-related genes including ANO1, CCND1, CTTN, FADD and ORAOV1 are involved in tumour cell proliferation, evasion of apoptosis, invasion, and migration." (PMID 28384287, 2017).
tumor (continued). "Genes in the KEGG WNT signaling pathway, including Ccnd1/2/3, Myc and Tcf7l1, were down-regulated in the transcriptome of G3 MB tumorspheres overexpressing WDR11, consistent with reduced tumor progression." (PMID 29029386, 2017). "Histological examination, CD20 and cyclin D1 analyses, and flow cytometry confirmed MCL diagnosis, with tumours comparable to the original diagnosed MCL." (PMID 28416797, 2017). "Accordingly, tumour cell infiltration into the BM was almost completely prevented in KPT-330-treated mice, as shown by IHC labelling for cyclin D1 and CD20 cells in representative biopsy specimens from both groups." (PMID 29066743, 2017). "MiR-326, a recognized tumor-suppressing miRNA, has been found to target the 3′-UTR of the human CCND1 mRNA and promote cell apoptosis." (PMID 29109913, 2017). "Because c-Myc and CCND1 play triple roles as HR genes, Roniciclib targets and components of an ESC-like tumour active signature, we expected their expression to decrease in response to the potential HR-NB drug Roniciclib." (PMID 28246384, 2017). "Tumours in this subset expressed FGFR3 and CCND1 as determined by IHC at the same levels as the Uro tumours, indicating a Uro‐related phenotype." (PMID 28195647, 2017). "DISC1, β-catenin, Cyclin D1, and Ki-67 levels increased from well- to poorly-differentiated NSCLC tissues, and increased with increasing tumor grade." (PMID 29029423, 2017). "As a member of the D-type cyclin family, cyclin D1 (CCND1) was a proto-oncogene and a good biomarker for tumor progression, found to be deregulated in several cancers, including RCC." (PMID 29113352, 2017). "Endogenous cyclin D1 maintained abundance of stromal cell-derived factor 1 (SDF-1α), also called CXCL12, which plays a central role in the promotion of tumor growth and angiogenesis." (PMID 29137220, 2017). "After treating with ESM1 siRNA in SK-Hep1 hapatocellular carcinoma cells, the cell cycle was arrested at the G1/S phase with down-expression of cyclin D1 and CKD4, but up-expression of PTEN, which had tumor suppressing function." (PMID 28108731, 2017). "Among these genes, many are involved in tumour suppression [e.g. RB1], apoptosis [e.g. BCL2L1], the cell cycle [e.g. CCND1, CCND2] or protein kinases [e.g. KIT, GSK3‐β]." (PMID 28539478, 2017). "Within this network, several genes were identified namely CCND1, RELA, TP63, and EGFR as being major contributors to tumour cell proliferation, immortalization, and metastasis in oral tumourigenesis." (PMID 28384287, 2017). "Since GSK3β induces phosphorylation and degradation of its downstream targets, and some GSK3β substrates are key proteins for promoting cell survival, such as β-Catenin, Cyclin D1, eIF2B and MYC, it was initially considered as a tumor suppressor." (PMID 28800359, 2017). "Both the proliferation assay in vitro and tumor growth assay in vivo showed that 7E inhibited cyclin D1-mediated tumor growth, which indicates that IL-20 has an important regulatory role in HCC progression through cyclin D1." (PMID 29242565, 2017). "The EWS/FLI-1 fusion product promotes tumor angiogenesis by upregulating VEGF-A expression, and in our study, Fli-1 knockdown attenuated the expression of Ki-67, VEGF, and cyclin D1 proteins." (PMID 28418872, 2017). "We selected four - cyclin D1 and p 21 that interfere in cell cycle and are related with cell proliferation, EGFR and VEGF related with angiogenesis and tumor progression." (PMID 28938543, 2017). "To this end, we measured the protein levels of cyclin D1, phospho-Smad2/3, and Smad4 in 40 of HCC tumor tissues." (PMID 28415588, 2017). "The increased p21WAF1 expression inhibited cyclin D1/CDK4 complex activity, which explains cell cycle arrest in the G1 phase, and the cell cycle arrest contributed to the 7E-induced inhibition of tumor growth." (PMID 29242565, 2017).
tumor (continued). "Bcl-XL and cyclin D1 equip tumor cells with chemoresistance and meanwhile the release of VEGF promotes angiogenesis to guarantee the nutritional supply for tumor cells." (PMID 28360909, 2017). "The effect of LAST on cyclin D1/CCND1 was further verified in normal HAFF cells and tumor H1299 and HCT116 cells." (PMID 29199958, 2017). "Forced expression of activated STAT3 in fibroblast cell lines resulted in 3-6 fold up-regulation of MYC, CCND1 (coding for cyclin D1) and BCL2L1 (BCL-XL) mRNA, and permitted tumor formation in nude mice." (PMID 29207662, 2017). "Cyclin D1 and VEGF, all regulated by STAT3, are major players in tumor metastasis and has been shown to mediate tumor invasion." (PMID 26911335, 2016). "Cyclin D1 (CCND1) overexpression is predominantly correlated with early cancer onset, tumor progression, shorter cancer patient survival and increased metastases." (PMID 27766950, 2016). "The decreased expression of CDK4, CDK6 which were directly inhibited by p16, along with the down-regulated expression of Cyclin D1, E2F1 and pRb confirmed the anti-tumor function of miR-877-3p was the due to p16 activation." (PMID 27429046, 2016). "Suppression of cyclin D1 and cyclin A by DACH1 negatively regulates cell cycle progression and thereby blocks cellular proliferation and tumor growth in various cancers." (PMID 27203207, 2016). "Results showed that Ki67, CCND1 and CCND2 were significantly downregulated in miR-146a-5p-stably-overexpressing tumor tissues." (PMID 27494902, 2016). "The correlation of Tspan5 expression with the expression of p27, p15, cyclin D1, CDK4, pRB and E2F1 in vivo are also revealed in xenografted tumours." (PMID 27223087, 2016). "IHC staining demonstrated that upregulation of Tspan5 significantly increased the expression of p27 and p15 but dramatically decreased the expression of cyclin D1, CDK4, pRB and E2F1 in xenograft tumours compared to control tumours (all P<0.001)." (PMID 27223087, 2016). "By immunohistochemistry, the tumor was positive with CK7, vimentin, PAX-8, racemase, RCC marker, AE1/AE3, 34βE12, carbonic anhydrase IX, CD10, and cyclin D1(SP4-R clone, Ventana, USA)." (PMID 27158455, 2016). "The miR-15b/miR-16-2 cluster, which is located in 3q25, has also been reported to act in tumor suppression by targeting BCL2, BM1, CCND1 and SUZ12." (PMID 27195958, 2016). "It has been shown that β-catenin can regulate WNT11, Cyclin D1, and MMP7 in many tumor cells, and so we next examined the role of CTNND1-mediated modulation of these genes." (PMID 27193094, 2016). "Tissue microarrays (TMA) based immunohistochemical stains were used to validate the protein expression of cyclinD1 (CCND1) and were scored semi-quantitatively from 0 to 3+ on the basis of absence or presence of staining intensity in the tumor cell." (PMID 27766950, 2016). "Statistically significant differences emerged in the distribution of EGFR, CCND1 and ESR1 CNVs according to ER, HER2, MIB1 and tumor size (T) status." (PMID 27765917, 2016). "More importantly, either upregulation of p15 and p27 or downregulation of cyclin D1, CDK4, pRB and E2F1 in tumour cells were also found in xenografted tumours of GC." (PMID 27223087, 2016). "Further studies have shown that miR-15a and miR-16-1 act as putative tumor suppressors by targeting BCL2, BMI1 CCND1, MCL1 and WNT3A in CLL, melanoma, as well as colon, bladder, ovarian and prostate cancers." (PMID 27195958, 2016). "The RB tumor suppressor pathway is frequently altered through deletion of CDKN2A (p16; ∼35%) or amplification of CCND1 (cyclin D1; ∼94%) in HNSCC." (PMID 26909611, 2016). "Second, we studied the effects of HOXA1 on GC cell proliferation, migration, invasion, cell cycle progression, and xenograft tumor formation by knocking down the expression of HOXA1, and we found that the expression of cyclin D1 was also decreased." (PMID 26791264, 2016).